CD4 (CD4 molecule)
Diseases named in the same sentence as CD4 in open-access papers (continued):
Sharing a sentence is not in itself a finding about the gene and the disease.
tumor (continued). "The overexpressions of ERCC1 and ACTL6A were found to significantly enhance the infiltration of CD8+ T-cells, macrophages, dendritic cells, CD4+ T-cells, and B-cells into HNC tumor cells." (PMID 40510426, 2025). "Accumulated tumor antigen-specific LIGHT+CXCL13+IL-21+ Tfh cells and TLS decreased tumor growth in a CD4+ T cell and CXCL13-dependent manner." (PMID 40475770, 2025). "This phenotypic shift in both the spleen and TME indicates effective tumor targeting by cytotoxic CD8+ T cells, potentially supported by IL-2 secretion from CD4+ T cells in both compartments." (PMID 40343532, 2025). "The association between elevated T-reg cell percentages (CD4 + FOXP3 +) at the tumor core and worse CSS in patients in our study might also indicate the existence of an intratumoral immunosuppressive environment that allows tumor cells to evade immune surveillance." (PMID 39751643, 2025). "Given the crucial role of T cells within the tumor microenvironment, we evaluated cytokine production by CD4+ and CD8+ T cells that infiltrate the tumor." (PMID 41463372, 2025). "Another study demonstrated that CAF significantly increased CXCL13 production by CD4+ and CD8+ T cells via TGF-β, thereby altering tumor TIME." (PMID 40244052, 2025). "Intriguingly, we observed a specific increase in the frequency of CD3+ T cells, CD4+ T cells, NKTs, and NKs in the ascites of Tnfrsf14KD‐ID8 tumor‐bearing mice." (PMID 40105652, 2025). "In a recent study, CD4+ T-cell clones were traced via paired scRNA/TCR-seq across tumors, tumor-adjacent normal tissues, lymph nodes, and peripheral blood from NSCLC patients treated with ICB." (PMID 40634636, 2025). "The CD4+ cells serve to maximize proliferation and support the maintenance of a functional CD8+ T cell phenotype, which is essential for anti-tumor activity, during the initiation of culture." (PMID 40861448, 2025). "This enhanced therapeutic response was accompanied by a robust immune infiltration of CD4 + and CD8 + T cell populations in the tumor tissues." (PMID 39810240, 2025). "For example, we identified regulatory CD4 T (Treg) cells and memory CD8 T (Temra) cells that highly express MKi67 in the new dataset, both of which showed a clear increase in tumor tissues." (PMID 39354287, 2025). "In HPV-positive tumors, PD-L1+ tumor cells were enriched at the tumor-immune interface, and ICOS+ CD4 T- cells were enriched in the tumor core, suggesting enhanced tumor-reactive T-cell activity." (PMID 41254766, 2025). "Of note, the only difference we observed was in the tumor of one patient (patient GS.1225), where CD69 expression on CD4 and CD8 T cells was higher in the resected tissue compared to the UA tissue." (PMID 40002198, 2025). "The expression of PD‐1 was increased in DNT, CD4+ naive T cell, CD4+ Tem, CD8+ Tcm and CD8+ Tem cells in the tumour site, while the expression of CD39 was also up‐regulated in CD4+ Tcm, CD4+ Tem, CD4+ Treg and CD8+ Tem cells." (PMID 39934971, 2025). "STAT4pPOS cells were found in 12.6% of the CD8 T cells, 3.7% of the CD4 T cells, and 2.3% of the NK1.1 cells in the TME of a CT-2A tumor treated with rIL-12." (PMID 40842154, 2025). "After CD4+ T cells infiltrate the TME, they interact with Plac1+ tumor cells via direct cell‐cell communication." (PMID 40056047, 2025). "The immune system processes and presents TAAs to T cells, thereby activating CD4+ helper T cells to support immune signaling and CD8+ cytotoxic T lymphocytes to eliminate tumor cells directly." (PMID 41614820, 2025). "We observed that in tumor tissues with HNRNPC knockdown, we observed a significant reduction in the expression of CD4 and F4/80 compared to the control group with intact HNRNPC expression." (PMID 39735682, 2025). "Inhibiting the Dectin-1-Gal-9 signaling pathway reprograms CD4 and CD8 T cells to promote anti-tumor immune responses." (PMID 40134029, 2025).
tumor (continued). "In tumor tissues, the group expressing high levels of FAM111B exhibited significantly higher CD8+ T cell, CD4+ T cell, Treg, CD4+ Teff cell, M1 macrophage, neutrophil, and DC infiltration." (PMID 40564014, 2025). "We also interrogated the role of CD4+ and CD8+ T cells in the antitumor activity of ICIs plus Y33 IC in CT26 tumor-bearing mice." (PMID 40789741, 2025). "Tumor-infiltrating lymphocytes (TILs)—including CD8+ and CD4+ T-cells, regulatory T-cells (Tregs), and B-cells (CD20+)—constitute a key element of anti-tumor immune surveillance." (PMID 40725022, 2025). "Examining T-bet, a crucial regulator of T helper 1 (Th1) cell generation, effector differentiation, and function in tumor-infiltrating lymphocytes, we noted a significant increase in Tbet+ cells in CD8+ and CD4+ T cells post-treatment." (PMID 40580480, 2025). "CD4+ T cells coordinate the immune response through cytokine release and CD8+ T cells directly lyse tumor cells by destroying tumor cells that Neomaxis recognize as distinct to neoantigens." (PMID 40688030, 2025). "The efficacious hgp10025–33-pulsed bm12 mBMDC vaccine increased tumor-infiltrating hgp100/H2Db tetramer+ active CD8+ T cells and Th1 cells in tumors, suggesting improved cooperation between CD4+ and CD8+ T cells." (PMID 40857404, 2025). "IL-21 arming augmented the function of CD4+ and CD8+ T cells, potentiated the anti-tumor activity of OVV, and reshaped the tumor immune microenvironment in mouse models of glioblastoma multiforme." (PMID 40821119, 2025). "Compared to the tumor, TIM-1+CD4+ T cells, TIM-1+CD8+ T cells, and TIM-1+B cells exhibited higher density in the stroma (p < 0.0001, p < 0.0001, p < 0.0001, respectively)." (PMID 40519901, 2025). "Intratumoral administration of F. nucleatum in BC has been confirmed to reduce the number of infiltrated CD4+ and CD8+ cells, which are typical immune related T cells, thereby allowing tumor cells to evade immune surveillance." (PMID 39995663, 2025). "As compared with VCaP tumors from null × CD3–treated mice, KLK2 × CD3 treatment resulted in increased CD8+ and CD4+ T-cell infiltration, with a concomitant reduction of KLK2+ tumor cells as measured by the detection of KLK2 and cytokeratin." (PMID 40627156, 2025). "In parallel, CD4+/CD8+ CXCR5+T follicular helper cells and CD8+CD103+ tissue-resident memory T cells were observed infiltrating in tumor tissues, Moreover, CD200 expressing B (CD20+CD200+) and T cells (CXCR5+CD200+) accumulated in the DCB groups." (PMID 40404633, 2025). "Enhanced DC maturation in tumor-draining lymph nodes and elevated CD8+/CD4+ memory T cell populations confirmed sustained immune memory activation, underscoring the nanovaccine’s capacity to prevent recurrence and metastasis." (PMID 40892295, 2025). "After subcutaneous immunization of mice with BTCs, infiltration of CD4+ and CD8+ T cells in the tumor tissue significantly increased, while immunosuppressive regulatory T cells decreased." (PMID 41179690, 2025). "The population and phenotypic characterization of tumor-infiltrating lymphocytes were then evaluated via CD3, CD4, and CD8 antibodies incubation with isolated lymphocytes from spleen tissues." (PMID 40739587, 2025). "In contrast, Texh_CD4, Treg, and Tactivated_CD4 cells exhibited higher levels of PD-1 expression, while HGSOC tumor cells displayed low PD-L1 (or CD274) expression level." (PMID 40260248, 2025). "Additionally, immune cell proportions estimated by CIBERSORT revealed differences in tumor immune infiltration: while CD8+ T cells were more abundant in the high-risk group, low-risk patients exhibited higher levels of activated dendritic cells, CD4+ memory T cells, and fewer regulatory T cells." (PMID 40475762, 2025). "These cytotoxic CD4+ T cells are clonally expanded, exhibit MHC class II-restricted tumor-killing activity, and are correlated with improved therapeutic outcomes." (PMID 40634636, 2025).
tumor (continued). "IF analysis demonstrated CD4+ and CD8+ T cell infiltration at tumor peripheries and pancreas-adenocarcinoma borders in partial responders." (PMID 41041061, 2025). "Previous studies have shown that during the progression of CIN to CC, TICs in TIME are gradually dominated by CD8+ T cells and macrophages, and the CD4/CD8 ratio is reversed, which implies a decrease in the body’s anti-tumor immunity." (PMID 40352921, 2025). "FGFR2+ tumors also demonstrated separation between both CD4+ T cells and CD8+ T cells and tumor cells as compared to both IDH1+ iCCA and FGFR2 WT/IDH1 WT (p<0.001)." (PMID 39969434, 2025). "In the context of RMS, the TME is enriched with CD4+ CTLs that can be stimulated by fusion peptides derived from the PAX-FKHR fusion protein in RMS cells, leading to the lysis of tumor cells." (PMID 41007114, 2025). "In vivo, treated humanized mice showed increased CD4+, CD8+, and NK cell frequencies in peripheral blood and within tumors, correlating with reduced tumor burden." (PMID 40733726, 2025). "These therapies work based on the activation of CD4, CD8, and NK T lymphocytes, which migrate to the tumor parenchyma to promote tumor cell death and slow down tumor growth." (PMID 40733140, 2025). "CD3+, CD4+, and CD8+ immune cell subsets were determined in pre-treatment and on-treatment (20 day) formalin-fixed paraffin-embedded (FFPE) tumour blocks from n = 13 patients." (PMID 40468999, 2025). "High levels of infiltration by B cell naives, M1 macrophages, CD4+ T cells, and CD8+ T cells within tumor tissue constitute a potential indicator of favorable prognosis in BC patients." (PMID 41415282, 2025). "Treatment with SDFZ‐8 resulted in a more significant increase in tumor‐infiltrating lymphocytes (TILs) than SAHA, particularly in the populations of CD4+ T cells and CD8+ T cells." (PMID 41267925, 2025). "After detection of tumor-infiltrating CD4+ T cells and GSDMD-N expression by immunofluorescence, the ratio of GSDMD-N+ CD4+ T cells was calculated." (PMID 40759573, 2025). "CD3+CD8+ CTLs, CD3+CD4+ T lymphocytes, and CD3+CD8+CD107a+ activated CTLs were more abundant in healthy mice before implantation compared with tumor‐bearing mice after tumor growth." (PMID 39749673, 2025). "This point is relevant as it is well-known that the immune response needs both the help mediated by the recognition of CD4+ T cells of MHC-II-restricted peptides and the lytic activity of CD8+ T cells restricted to MHC-I antigens to eliminate tumor cells." (PMID 40677711, 2025). "Additionally, correlations between CD68 expression and six TIICs (B cells, CD4+ T cells, CD8+ T cells, macrophages, NK cells, and cancer-associated fibroblasts) or four common TICs (PDCD1, CTLA4, IDO1, and CD40) were assessed using the Tumor Immune Estimation Resource (TIMER)." (PMID 40918116, 2025). "In contrast, T cell immunoglobulin and mucin-domain containing-3 (TIM-3) expression was higher on CD4+ and CD8+ T cells in both primary tumours and draining lymph nodes of SCC patients compared to AC patients." (PMID 40639721, 2025). "First, in vitro findings revealed that LSD1 deletion led to an augmentation in the population of anti‐tumour immune cells, including CD8+ cells, CD4+ naive T cells and NK cells." (PMID 40356247, 2025). "Studies have shown that normal thyroid tissue adjacent to tumors often exhibits a higher density of immune cells, particularly CD3+, CD4+, CD8+, and CD20+ lymphocytes, indicating a robust immune response in non-tumor tissues." (PMID 40469283, 2025). "After anti‐CTLA‐4 therapy for prostate tumors, PD‐L1 and V‐domain Ig suppressor of T‐cell activation expression significantly increases on CD4+ T cells, CD8+ T cells and CD68+ macrophages, and PD‐L1 expression increases on tumor cells." (PMID 41346571, 2025). "In contrast, while primary tumor rejection required both CD4 + and CD8 + T cells, rechallenge tumor clearance demonstrated dependency on CD4 + T cells alone." (PMID 40585246, 2025).
tumor (continued). "We found that CD4+ T, CD8+ T, proliferating T cells (T-pro), and NK cells activated the anti-tumor function of TANs through TNF and IFNG, including cytotoxicity, cytokine production, chemotaxis, migration and IFNγ signaling." (PMID 40360503, 2025). "In the GSE120575 dataset, which includes tumor samples from 48 SKCM patients treated with checkpoint inhibitors, MZF1 expression was found predominantly in CD4 Tconv cells, Treg cells, CD8 T cells, and CD8 Tex cells within the SKCM microenvironment." (PMID 40655141, 2025). "CD4+ T lymphocytes are also important as they are involved in the activation and regulation of CD8+ T lymphocyte responses in the tumor microenvironment." (PMID 41303843, 2025). "There is increasing evidence that CD4+ and CD8+ T cells predominantly express CCR5, which is important for T lymphocyte infiltration in tumor beds." (PMID 41029711, 2025). "Therapeutically, this led to strong downregulation of PD-L1 protein, which reduced tumor immune escape, and enhanced infiltration of CD8+ and CD4+ T cells at the tumor site." (PMID 41471822, 2025). "Experimental results demonstrated that the DPPA-TRPP/Tab nanoplatform not only increased tumor accumulation but also suppressed CAF formation and enhanced the activation of CD4+ and CD8+ T cells." (PMID 40038745, 2025). "Camrelizumab, a PD-1 inhibitor developed in China, targets PD-1 on CD4+ and CD8+ T lymphocytes, B cells, and natural killer cells, effectively countering PD-1-mediated immunosuppression and preventing tumor immune escape." (PMID 40621454, 2025). "T cells from tumor tissues were extracted and annotated into four types (CD4 + T cells, CD8 + T cells, CD4 + Tregs, and NK T cells) based on Cell Mark 2.0 and literature references." (PMID 41406096, 2025). "Subsequently, T cell receptors can recognize tumor antigen–MHC complexes, leading to activation and expansion of cytotoxic CD8+ and CD4+ T cells, respectively." (PMID 40608411, 2025). "Inhibition of VEGF signalling has been shown to stimulate CD4+ and CD8+ T cell activation and tumour infiltration, thereby reprogramming the tumour microenvironment." (PMID 40346068, 2025). "CHIs combined with EGFR-TKIs improved the expression of CD3+ and CD4+ T cells, as well as the CD4+/CD8+ ratio, implying that CHIs exert their anti-tumor activity by augmenting human immune function." (PMID 41347160, 2025). "The exogenous tumor antigens in cancer vaccines can be delivered to APCs, particularly dendritic cells (DCs), to induce CD4+ T-cell and cytotoxic T lymphocyte (CTL) responses, thereby eliminating tumor cells." (PMID 40244296, 2025). "These CD4+ T cells were ex vivo expanded with the treatment of Δ35 mM NaCl, anti-CD3/CD28, IL-2 and IL-7 along with heat-killed tumor cells." (PMID 40563574, 2025). "It has been reported that liposomal vaccines can carry both Th and cytotoxic T lymphocyte epitopes and activate both CD4+ and CD8+ T cells, producing specific anti-tumor immune response in mice models with therapeutic and preventive effects." (PMID 40342927, 2025). "Strikingly, CD4 and CD8 T cell depletion nearly completely abrogated the inhibitory effect of ERBB2 KO on SCLC tumor growth in immunocompetent mice." (PMID 41361170, 2025). "It selectively promotes the transport of naïve and memory T and B lymphocytes, leading to increased tumor infiltration by CD3+, CD4+, and CD8+ cytotoxic T lymphocytes (CTLs)." (PMID 41375025, 2025). "The elevation of CXCL1 was found to promote the migration of M2 TAMs while simultaneously disrupting the aggregation of CD4+ and CD8+ T cells within tumor microenvironments." (PMID 40149492, 2025). "Myeloid-derived suppressor cells (MDSCs) also contribute by engulfing tumor debris and presenting neoantigens via MHC class II to CD4+ T cells." (PMID 41249701, 2025). "We discovered that in mice intravenously injected with a mixture of CD4+ T and CD8+ T cells via the tail vein, JMS‐17‐2 significantly inhibited tumor progression." (PMID 39783838, 2025).
tumor (continued). "Here, we investigated the role of mIL2 expressed from an engineered Vaccinia virus Lister strain in 4T1 tumor-bearing syngeneic BALB/c mice and analyzed its effect on CD8+ T cells and CD4+ Tregs." (PMID 41050655, 2025). "CD4+ central memory T cells (Panel2-C17) also exhibited elevated CCR2 and CCR7 expression, potentially facilitating tumor-directed migration." (PMID 41194936, 2025). "In epithelial ovarian cancer, for example, the chemokine CCL22 recruits CD4+CD25+FOXP3+ cells, leading to suppression of antitumor immunity and favoring tumor progression." (PMID 41394821, 2025). "The co-administration of CD4+ CAR-T and CAR-NK cells resulted in tumor regression and improved survival in 3 out of 5 mice." (PMID 40376677, 2025). "It has been recently shown that within tumor tissue close interactions between both CD8+ and CD4+ T cells at cross-presenting DCs form effective immunological triads important for driving antitumoral T-cell immunity." (PMID 39789356, 2025). "It has been demonstrated that a high percentage of CD3+, CD4+, and CD8+ T cells in the tumor microenvironment of DLBCL correlates with a favorable prognosis." (PMID 40391074, 2025). "Through quantifying the relative overlap of clones between different phenotypes within the CD4 and CD8 T cell populations, lineage patterns can be discerned over the history of the tumour prior to sampling." (PMID 39915477, 2025). "Research has shown that adaptive immunity components CD4+ T cells, CD8+ T cells, IL12, and IFNγ are in charge of keeping tumor cells in balance by exerting immune selection pressure." (PMID 41019045, 2025). "In the CD4+ compartment, both CD134 (1.590 vs. 0.811) and CD137 (0.570 vs. 0.273) were significantly upregulated in tumor tissues (both P < 0.05), indicating enhanced activation potential or a regulatory phenotype skew." (PMID 41181122, 2025). "This interaction is crucial for activating CD4+ helper T cells, which in turn help activate CD8+ cytotoxic T cells, thereby enhancing the overall anti-tumor immune response." (PMID 39911388, 2025). "Nevertheless, analyzing different tumor layers obtained with 5‐ALA‐assisted surgery, we observed a statistically significant positive correlation between OS and the percentage of CD4+CD103+ (p = 0.038) and CD8+CD103+ (p = 0.015) T cells in the necrotic core." (PMID 40498413, 2025). "Analysis using the TIMER database demonstrated a positive correlation between CXCL3 expression and immune cell infiltration, including macrophages, neutrophils, B cells, CD4+ T cells, CD8+ T cells, and dendritic cells within the tumor microenvironment." (PMID 41259383, 2025). "Regarding tumor-infiltrating immune cells, MES samples demonstrated higher levels of infiltration by activated dendritic cells, Tfh cells, and memory CD4+ T cells than ABS subtype in both METABRIC and GSE96058." (PMID 39649843, 2025). "ERBB2 blockade alone resulted in a significant increase of activated CD4+ and CD8+ T cells in the tumor." (PMID 41361170, 2025). "PD-L1 on tumor cells binds to PD-1 on T cells, thereby inhibiting the cytotoxic activity of CD8+ T cells and possibly other immune cells, including CD4+ T cells." (PMID 41296438, 2025). "Mice treated with thiostrepton exhibited comparable percentages of tumor‐infiltrating lymphocytes (TIL—CD3, CD4, or CD8)." (PMID 40820379, 2025). "NeoAg-specific CD4+ T cells can also secrete inflammatory cytokines such as IFN-γ and TNF within the tumor microenvironment (TME), which can directly inhibit tumor growth, suppress pro-tumor accessory cells, and inhibit tumor vasculature." (PMID 40196575, 2025). "In contrast, CD4+ T cells recognise tumour antigens bound to MHC class II molecules on antigen presenting cells and help to initiate tumour‐specific cytotoxic T lymphocyte (CTL) responses." (PMID 40172096, 2025).